ACSL4 (acyl-CoA synthetase long chain family member 4)
Diseases named in the same sentence as ACSL4 in open-access papers (continued):
Sharing a sentence is not in itself a finding about the gene and the disease.
tumor (continued). "In the present study, IHC staining of OS tissues proved that the presence of elevated ACSL4 in OS tissues, with its expression level increasing in accordance with tumor malignancy." (PMID 38564125, 2025). "In pancreatic cancer, exosomal ACSL4 secreted by CAFs promotes polyunsaturated fatty acid metabolism, significantly reducing the sensitivity of tumor cells to chemotherapy drugs such as gemcitabine." (PMID 40755775, 2025). "Specifically, CD36, FABP4, PLIN1, SCD5 and ACSL4 were significantly downregulated in tumor samples (p < 0.05)." (PMID 40860798, 2025). "In contrast, ACSL4 deletion can protect CD8+ T cells from ferroptosis but impairs anti‐tumour activity." (PMID 40045458, 2025). "This activation occurs through altering tumor cell lipid metabolism, enhancing the integration of AA with phospholipids containing C16 and C18 acyl chains, thereby promoting ACSL4‐dependent ferroptosis." (PMID 40919133, 2025). "It is also encouraging that ACSL4 deletion effectively reduced the rate of tumor growth in xenograft tumor model." (PMID 38564125, 2025). "Tumor heterogeneity leads to significant differences in the sensitivity of different cancer types to ferroptosis: gastric cancer is resistant due to low ACSL4 expression levels, while liver cancer is more sensitive due to high SLC7A11 expression levels." (PMID 40535125, 2025). "To date, the function of ACSL4-mediated ferroptosis in numerous diseases, including tumor growth and intestinal ischemia/reperfusion, has been investigated." (PMID 40332005, 2025). "CD8+ T cells and CAR-NK cells promote ferroptosis by secreting IFN-γ, which downregulates system Xc- and upregulates ACSL4, enhancing lipid peroxidation and inhibiting tumor growth." (PMID 40919170, 2025). "Another metabolic regulator, acyl-CoA synthetase 4 (ACSL4), is involved in lipid metabolism and steroidogenesis, with pharmacological inhibition reducing tumor growth and improving chemotherapeutic efficacy." (PMID 40722763, 2025). "Palmitoleic acid and oleic acid, two common C16 and C18 fatty acids in the blood, promote ACSL4-dependent tumor ferroptosis induced by IFN-γ plus AA." (PMID 40539046, 2025). "Radiation therapy-induced upregulation of ACSL4 has been shown to enhance lipid synthesis and oxidative stress, to promote ferroptosis and modulating ROS levels in tumor cells following irradiation." (PMID 41288931, 2025). "ACSL1, ACSL3, and ACSL4 have been reported to promote tumor proliferation and sustain stemness by potentiating fatty acid oxidation (FAO)." (PMID 40507798, 2025). "In the presence of arachidonic acid and other fatty acids, IFN-γ stimulates ACSL4 expression, alters tumor cell lipid metabolism, and promotes ferroptosis." (PMID 41326356, 2025). "ACSL4-mediated ferroptosis is influenced by the immune and metabolic environment, making it a potential target for anti-tumor immunotherapy." (PMID 41288931, 2025). "In vivo studies also confirmed that POL can significantly inhibit the growth of OC xenografts, as manifested by a decrease in tumor volume and weight, and a significant increase in ACSL4, MDA and ROS levels in tumor tissues." (PMID 40539051, 2025). "There are still some shortcomings in this research, and the signaling pathways through which miR-145-5p/ACSL4 regulate tumor advancement can be further explored in future studies." (PMID 39652084, 2025). "Targeting ACSL4 with inhibitors like PRGL493 suppresses tumor growth by reducing energy production, offering a promising therapeutic strategy for BQ-high patients." (PMID 40507798, 2025). "Immunohistochemistry analysis revealed that Ki-67 positivity was markedly reduced in tumor tissues following either ACSL4 silencing or miR-145-5p overexpression." (PMID 39652084, 2025). "This process, facilitated by ACSL4, triggers lipid peroxidation and consequent ferroptosis in tumor cells, with a positive feedback loop involving PKCβII-mediated phosphorylation of ACSL4." (PMID 40285867, 2025).
tumor (continued). "Mechanistic studies have demonstrated that ACSL4 enhances metastasis by increasing the fluidity of the plasma membrane, thereby promoting tumor cell migration and invasion." (PMID 40919170, 2025). "In summary, ACSL1 and ACSL4 are suspected to contribute to tumor progression in most of the tumor types examined, whereas ACSL5 appears to hinder tumor growth." (PMID 40932861, 2025). "COX2 and ACSL4 expression in the tumor tissues of the sh-circSIRT5 group was significantly lower than in the sh-NC group, and in the circSIRT5 overexpression group, they were significantly higher than in the Vector group." (PMID 39223162, 2024). "Canagliflozin treatment more effectively suppressed tumor growth in mice inoculated with ACSL4-low cells compared to those with ACSL4-high cells." (PMID 39563427, 2024). "By quantitative mass spectrometry analysis with anti-ACSL4 immunoprecipitates from lysates of HONE1 bulk tumor cells or TRCs, we identified kinases PCK2, PKM2 and PFKP, as well as phosphatase PPM1G, from the top 250 most enriched proteins in the precipitates." (PMID 38720107, 2024). "Western blot similarly confirmed that POL increased the protein expression levels of ACSL4 in mouse tumor tissues." (PMID 38503553, 2024). "Results indicated that oral administration of Panobinostat significantly impeded tumor growth, and this inhibition was reversed by ACSL4 knockdown." (PMID 39261475, 2024). "In T cells, the coordination between fatty acids, IFN-γ, and ACSL4 mediates tumor ferroptosis and immune responses." (PMID 38965216, 2024). "We extracted the entire protein of the tumor and verified the ACSL4 expression of the tumor by western blotting, which was found to be consistent with in vitro." (PMID 38370339, 2024). "This is consistent with our findings that silencing CK19 promotes ferroptosis and inhibits tumor growth by activating ACSL4 expression and inhibiting GPX4 expression." (PMID 38987531, 2024). "The inhibition of acetyl-CoA synthetase (ACSS2) and long-chain acyl-CoA synthetase 4 (ACSL4) has resulted in a marked decrease in tumour growth and therapeutic sensitivity in various cancers." (PMID 38610991, 2024). "It has been reported that the tumor microenvironment of ACSL4−/− animal models displays decreased infiltration of CD8+, IFNγ+CD8+, TNFα+CD8+, and CD4+ T cells compared to the tumor microenvironment of ACSL4+/+ animal models." (PMID 38778030, 2024). "On the other hand, by siRNA screening, we observed that knocking down any of these genes did not change the sensitivity of TRCs to RSL3, whereas knocking down of ACSL4 or LPCAT3 significantly decreased the sensitivity of cells to RSL3 in bulk tumor cells." (PMID 38720107, 2024). "ACSL4-dependent tumor ferroptosis, induced by the combination of IFN-gamma and arachidonic acid, also triggers CD8+ T cell-dependent antitumor immunity." (PMID 38844964, 2024). "ACSL4 was found significantly overexpressed in tumor samples from patients who experienced relapse (n = 20) when compared to non-relapse (n = 12) (p = 0.0003)." (PMID 39174500, 2024). "T cell-derived interferon (IFN)-γ in combination with AA induces immunogenic tumor ferroptosis by activating AA to arachidonoyl-CoA by ACSL4." (PMID 38719806, 2024). "Recent studies have shown that IFN-γ can downregulate SLC3A2 and SLC7A11 while upregulating ACSL4, promoting tumor cell ferroptosis." (PMID 38965216, 2024). "LPCAT3 and LOX are involved in the integration of arachidonic acid into the membrane phospholipids and the oxidation of these phospholipids, respectively, promoting IFN-γ and arachidonic acid-induced ACSL4-dependent tumor ferroptosis." (PMID 38965216, 2024). "A significant association was observed between high ACSL4 levels and extrahepatic CCA, tumor growth type, and elevated alanine transferase (ALT)." (PMID 39335604, 2024). "miR-22-3p directly targets the ACSL4 gene of tumor cells, thereby inhibiting cell iron death induced by the eradicator of Ras and ST and accelerating tumor progression." (PMID 39228519, 2024).
tumor (continued). "Compared to ACSL4-WT, tumor cells re-expressing ACSL4-T679A showed dampened enzymatic activity and decreased ferroptosis." (PMID 38720107, 2024). "CARM1 promotes tumor progression by methylating ACSL4 while inhibiting CARM1 can increase tumor cell sensitivity to ferroptosis, thereby promoting immunogenic cell death of tumor cells." (PMID 39273090, 2024). "It was shown that inhibition of ferroptosis by ectopically expressing GPX4 or silencing the expression of ACSL4 can reduce necrosis by 47% or 58–68%, respectively, and prolong the survival of tumor-bearing mice." (PMID 38806658, 2024). "Among ACSL family members, ACSL4 was found to be significantly upregulated in HCC tissues compared to adjacent non-tumor tissues, as revealed by bioinformatic analyses and transcriptional analysis." (PMID 39563427, 2024). "circSCN8A ectopic expression inhibits migration, proliferation, invasion, and tumor growth in animal models and increases ferroptosis via the circSCN8A/miR-1290/ACSL4 axis." (PMID 38778030, 2024). "Consistently, inhibition of ACSL4 via rosiglitazone almost abolished ferroptosis differences between bulk tumor cells and TRCs." (PMID 38720107, 2024). "Compared with the control group, the tumor volume was significantly decreased after sorafenib treatment, and the expression of ACSL4 and 4HNE were enhanced." (PMID 38839744, 2024). "We further purified ACSL4 from HONE1 bulk tumor cells and TRCs, and enzyme activity assay indicated that ACSL4 from TRCs resulted in a lower product (AA-d8-CoA) formation than those from bulk tumor cells." (PMID 38720107, 2024). "Most of these studies were performed in the context of tumours, and the regulatory mechanisms of ACSL4 and TFRC in other benign diseases still need to be investigated." (PMID 38834654, 2024). "Collectively, our findings underscore the pivotal role of ACSL4-mediated lipid peroxidation and ferroptosis in mediating the tumor-suppressive activity of LHPP." (PMID 39261475, 2024). "Subsequent studies indicated that IFNγ and arachidonic acid from the tumor microenvironment jointly induce tumor cell ferroptosis through ACSL4." (PMID 39402302, 2024). "Our previous study reported that ACSL4-high expression in tumor tissue was correlated with good prognosis in HCC patients treated with sorafenib, due to ACSL4's role in promoting ferroptosis induced by sorafenib." (PMID 39563427, 2024). "CYP1B1 activated the PKC signaling pathway by degrading ACSL4, increased the expression of FBXO10, and promoted the ubiquitination and degradation of ACSL4, thereby making tumor cells resistant to ferroptosis." (PMID 39850905, 2024). "For instance, radiotherapy triggers ACSL4-dependent ferroptosis in various cancer cell lines and xenografted tumor-bearing mice." (PMID 38844964, 2024). "We observed that the total phosphorylation level of ACSL4 was lower in TRCs than in bulk tumor cells." (PMID 38720107, 2024). "The significant correlation between ACSL4 protein expression and a higher tumor grading in lung ADC indicates its role in ADC differentiation." (PMID 38539505, 2024). "As expected, the bulk tumor cells and TRCs from ACSL4-knockout cells showed similar PL unsaturation patterns and ferroptosis sensitivity, both of which were at similar levels with TRCs from wild-type (WT) cells." (PMID 38720107, 2024). "Collectively, ACSL4 plays a dual role in tumorigenesis, participating in lipid metabolism, cell proliferation, and regulation of the tumor microenvironment on the one hand, and mediating cellular ferroptosis on the other hand." (PMID 37372148, 2023). "Recent study has highlighted AA and IFN-γ coordinately induced tumor cell ferroptosis via ACSL4, which mediated immunogenic tumor ferroptosis." (PMID 37311754, 2023). "Supplementation of arachidonic acid in combination with checkpoint blockade is also able to enhance tumor ferroptosis and anti-tumor immunity via reprogramming ACSL4-mediated lipid metabolism." (PMID 37553341, 2023).
tumor (continued). "More recently, ACSL4 has been shown to mediate immunogenic tumor ferroptosis induced by cytotoxic T lymphocytes via IFNγ." (PMID 37306503, 2023). "ACSL4, a pro-ferroptotic gene, was experimentally established as a target of miR-22-3p in tumor cells." (PMID 36967385, 2023). "Although it has been reported that ACSL4 is a tumor suppressor that activates ferroptosis, many studies have suggested that ACSL4 is an oncogene that contributes to tumor progression." (PMID 38078907, 2023). "In tumor cells, the methylation pathway of ACSL4 is generally inhibited, leading to PTM changes or overexpression that promotes tumor cell proliferation." (PMID 37372148, 2023). "More importantly, among the five family isoforms, ACSL1 and ACSL4 promote uncontrolled cell growth, facilitate tumor invasion, and lead to evasion of programmed cell death." (PMID 37078067, 2023). "This discovery suggests that CARM1‐mediated ACSL4 R339 methylation is a vital regulatory mechanism for ferroptosis resistance and tumor progression." (PMID 37946697, 2023). "Depletion of ACSL4 in tumor cells blocks ferroptosis initiation, suppresses T cell response, and accelerates tumor progression." (PMID 37553341, 2023). "MiR-22-3p is packaged in exosomes and transferred from cardiomyocytes to tumor cells, where it represses the expression of ACSL4, a critical determinant of ferroptosis sensitivity." (PMID 36967385, 2023). "We confirm, for the first time, that ACSL4 is a tumor promoter in CHOL in vitro by Knockdown of ACSL4 in CHOL cell lines." (PMID 37193981, 2023). "ACSL4 can promote uncontrolled cell growth and enhance tumor escape from programmed cell death and invasion." (PMID 37056351, 2023). "IFNγ released from T cells is an activator of the ferroptosis regulator ACSL4 and can accelerate the incorporation of AA into phospholipids, subsequently inducing immunogenic tumor ferroptosis." (PMID 37840106, 2023). "Overexpression of miR-4291 or knockdown of ACSL4 reversed the effect of circLMO1 in facilitating ferroptosis, repressing proliferation, and decreasing tumor invasion of CC cells." (PMID 37025659, 2023). "ACSL4 is also a potential target for tumor treatment, as studies have demonstrated its inhibitory effect on glioma cell proliferation through the activation of the ferroptosis pathway." (PMID 37373168, 2023). "Based on the clinical evidence that ACSL4 has a potential role in CHOL tumor progression, we analyzed the expression of ACSL4 in BEC and 4 CHOL cell lines." (PMID 37193981, 2023). "Even more exciting, GPX4 expression is obviously reduced during tumor recurrence, whereas acyl-CoA synthetase long chain family member 4 (ACSL4) expression exhibits an obvious increase." (PMID 36937406, 2023). "ACSL4 “acyl-CoA synthetase long-chain family member-4”, which was involved in the hormonal regulation of steroidogenesis, had the second-highest mean tumor H score in our study." (PMID 36829466, 2023). "Next, we determined the correlation between CYP1B1 and ACSL4 in CRC tumor tissues, estimating by semiquantitative evaluation." (PMID 37059712, 2023). "Another study found that IFNγ generated in the TME by activated T cells paired with arachidonic acid affected spontaneous antitumor immunity in vivo by inducing tumor cell ferroptosis through acyl-CoA synthetase long-chain family member 4 (ACSL4)." (PMID 37213276, 2023). "In summary, we found and provided evidence that CARM1 inhibited ferroptosis, which is closely related to ACSL4 R339 methylation, and that its inhibitor suppressed tumor progression when combined with anti‐PD‐1." (PMID 37946697, 2023). "As a new mode of action for cytotoxic T-cell-mediated tumor killing, T-cell-derived IFN-γ stimulates ACSL4 and alters tumor cell lipid patterns by binding to arachidonic acid to induce ferroptosis in immunogenic tumor cells." (PMID 37894808, 2023). "Intratumoral depletion of ACSL4 or overexpression of GPX4 reduces tumor necrosis and aggressiveness." (PMID 36937406, 2023).
tumor (continued). "We used TIMER2.0 to explore the different expression of ACSL4 between normal and tumor tissue in various cancers." (PMID 37193981, 2023). "The specific mechanism is that IFN-γ stimulates ACSL4 and changes the lipid pattern of tumor cells, thereby increasing the binding of AA with C16 and C18 acyl-chain phospholipids." (PMID 37894808, 2023). "Depletion of ACSL4 resulted in a significant reduction in tumor growth and lung colonization of highly metastatic MDA-MB-231 cells." (PMID 38078907, 2023). "Mechanistically, CYP1B1 induced tumor cell resistance to ferroptosis by increasing ACSL4 ubiquitination and promoting its degradation." (PMID 37059712, 2023). "The tumor growth curve and IHC results showed that ACSL4 knockdown accelerated the growth of shCARM1 tumors by increasing Ki‐67 levels." (PMID 37946697, 2023). "The expression of ACSL4 is linked to the level of CD8 + T cell infiltration and affects subsequent anti-tumor immunity." (PMID 37193981, 2023). "Because of its important regulatory role in in the ferroptotic cell death process and its sensitizing effects on (tumor) cells towards ferroptosis, ACSL4 was also chosen as marker for ferroptosis in this study." (PMID 35530303, 2022). "IFN-γ synergistically promotes tumor ferroptosis along with fatty acids in the tumor microenvironment through ACSL4." (PMID 35847022, 2022). "Itraconazole induced cell proliferation and apoptosis, and increased HMGCS1 and ACSL4 expression in xenografted tumor A431 cells." (PMID 35242038, 2022). "While the expression of GPX4 decreased significantly during tumor relapse, ACSL4 showed a significant increase." (PMID 35530303, 2022). "ACSL4, a long-chain fatty acyl coenzyme, is closely related to the proliferation and migration of tumor cells." (PMID 35610340, 2022). "Other studies have shown that ionizing radiation (IR) not only induced the production of ROS in tumor cells, but also induced ACSL4 expression." (PMID 35126480, 2022). "Studies have shown that ACSL4 is involved in various biological processes, such as proliferation, apoptosis, migration, and invasion of tumor cells." (PMID 35237519, 2022). "Surprisingly, the ACSL4 level can be an independent predictor of complete response and tumor-free survival after TNBC neoadjuvant chemotherapy." (PMID 35911967, 2022). "After adjusting for tumor purity, ACSL4 was significantly positively correlated with the level of immune cell infiltration in SKCM and BRCA." (PMID 35126480, 2022). "Analysis on RCC patient samples demonstrated elevated ACSL4 expression in RCC tumor samples, comparing with the normal tissues, and this high ACSL4 level correlated with unfavorable prognosis of RCC patients." (PMID 35368896, 2022). "Transferrin receptor-mediated ROS promotes ferroptosis of human granulosa-like tumor cells via regulating ACSL4." (PMID 35242038, 2022). "Clinically, tumor ACSL4 correlates with T cell signatures and improved survival in ICB-treated cancer patients." (PMID 35610340, 2022). "On the other hand, IFNγ directly initiate arachidonic acid-induced tumor cell ferroptosis via activating ACSL4." (PMID 35882850, 2022). "IFN-γ stimulates ACSL4 and changes the lipid pattern of tumor cells, thereby increasing the binding of AA to C16 and C18 acyl-chain phospholipids." (PMID 35910359, 2022). "Suppressing the ACSL4 pathway reduces tumour progression and, furthermore, it increases the tumour sensibility to TMZ treatment." (PMID 35208642, 2022). "In LUAD, ACSL4 plays a tumor suppressor role by inhibiting tumor survival/invasion and promoting ferroptosis." (PMID 36147484, 2022). "The depletion of ACSL4 reportedly reduces tumor necrosis, proliferation, migration, and cell self-renewal ability." (PMID 36497375, 2022). "Recently, by using another murine tumor model it has been shown that arachidonic acid and IFNɣ coordinately induce tumor cell ferroptosis via ACSL4 and ACSL4-mediated immunogenic tumor ferroptosis." (PMID 35844506, 2022).